NFAT5 (nuclear factor of activated T cells 5)
Diseases named in the same sentence as NFAT5 in open-access papers (continued):
Sharing a sentence is not in itself a finding about the gene and the disease.
diabetes (continued). "The DNA-binding activity of NFAT5 was found to be increased in peripheral blood mononuclear cells from patients with diabetes with nephropathy compared to that in an uncomplicated group without nephropathy." (PMID 33015193, 2020). "New insights into the consequences of hyperglycemic osmotic stress in diabetes have revealed the involvement of the NFAT5, a tonicity-responsive transcription factor, as an important signaling molecule in diabetes." (PMID 26693099, 2015). "Moreover, NFAT5 regulates AR and PKCδ expression in diabetic in vivo models 166, highlighting the importance of the NFAT5-AR axis in the pathophysiology of diabetes." (PMID 40421201, 2025). "In addition, heterozygous (NFAT5+/−) mice have been documented to attenuate hippocampal inflammation in high-fat diet-induced diabetes compared with wild-type mice." (PMID 40831534, 2025). "Similarly, high glucose uptake contributes to elevated NFAT5 levels and contributes to pathophysiology, as observed earlier in diabetic retinopathy and diabetes mellitus." (PMID 38612478, 2024). "Berberine, a NFAT5-targeting therapy for diabetes complication patients, could inhibit the inflammatory effects without affecting its osmotic effects since the latter is involved in cellular homeostasis and cytoprotection." (PMID 33015193, 2020). "Recent studies have identified NFAT5 as an effective target therapy for diabetes." (PMID 33015193, 2020). "ROS inhibitors are potential NFAT5-targeting therapeutic agents for patients with diabetes." (PMID 33015193, 2020). "Recent studies revealed that NFAT5 is an effective therapeutic target for diabetes." (PMID 33015193, 2020). "NFAT5 haploinsufficiency attenuates adipogenesis and insulin resistance in mice with diabetes." (PMID 33015193, 2020). "The protective adaptation of NFAT5 cannot maintain normal functions in patients with diabetes." (PMID 33015193, 2020). "Angiotensin- (Ang-) II and platelet-derived growth factor- (PDGF-) BB are associated with prior cardiovascular events in diabetes and stimulate NFAT5 to regulate VSMC migration in the absence of hypertonic stress." (PMID 33015193, 2020). "As the course of diabetes progresses, the physiological function of NFAT5 is altered." (PMID 33015193, 2020). "Patients with dry eye syndrome, which commonly occurs in diabetes, may benefit from NFAT5-targeted therapy." (PMID 33015193, 2020). "Increased expression of NFAT5 is closely correlated with the progression of diabetes in patients." (PMID 33015193, 2020). "Additionally, NFAT5 activates inflammation at a very early stage of diabetes and induces persistent inflammation." (PMID 33015193, 2020). "NFAT5 functions upstream of the polyol pathway to regulate the progression of diabetes." (PMID 33015193, 2020). "Again, mice injected with NFAT5 siRNAs showed reduced streptozotocin-induced diabetic retinopathy, suggesting that transcriptional knockdown of NFAT5 using siRNAs can be a useful strategy to treat NFAT5-dependent autoimmune inflammatory diseases including RA and diabetes mellitus." (PMID 30873159, 2019). "However, chronic or excessive hyperosmolar conditions, whether localized (e.g., in the kidneys, central nervous system, or eye) or systemic (such as in diabetes), can push NFAT5 regulatory capacity into a pathological state." (PMID 40421201, 2025). "Thus, in diabetes therapy, NFAT5 target osmolytes can be supplemented." (PMID 33015193, 2020). "In individuals with normal glycemia, NFAT5 correlates with IL33/ST2, while in type 2 diabetes mellitus (T2DM), it inversely correlates with body fat percentage and directly correlates with soft lean mass percentage." (PMID 40421201, 2025). "In placental tissue from individuals with gestational diabetes, NFAT5 nuclear localization and SMIT expression increase, correlating with ceramide levels that contribute to a hyperosmotic stress environment, worsening diabetes outcomes." (PMID 40421201, 2025).
diabetes (continued). "Therefore, gene regulator NFAT5 could be a potential therapeutic target for diabetes." (PMID 33015193, 2020). "Finally, we studied NFAT5 as a biomarker of hypertonicity and HIF-1α as a biomarker of hypoxia conditions because both molecules are closely related to diabetes." (PMID 35046888, 2021). "NFAT5 is an upstream regulator of vascular angiogenesis that induces VEGF-C, cyclooxygenase (COX)-2, and SGK1, which stimulate atherosclerotic lesion development and aggravate vascular complications of diabetes." (PMID 33015193, 2020). "The expression level of NFAT5 was significantly higher in patients with type 1 diabetes mellitus (T1DM) and nephropathy compared to that in patients without microvascular complications." (PMID 33015193, 2020). "NFAT5 may also have unknown and widely distributed effects rather than an osmotic protective role singly in diabetes." (PMID 33015193, 2020).
rheumatoid arthritis (15 papers, 2015 to 2025). A chronic, systemic autoimmune disorder characterized by inflammation in the synovial membranes and articular surfaces. "In previous studies, since complete loss of NFAT5, specifically deletion of exons 6 and 7, results in late gestational or perinatal lethality, NFAT5-Het mice have mostly been used for in vivo studies, such as hippocampal inflammation, hypothalamic inflammation, and rheumatoid arthritis studies." (PMID 33806698, 2021). "In rheumatoid arthritis (RA), a disease characterized by high levels of pro-inflammatory cytokines, NFAT5 is translocated to the nucleus and highly expressed in fibroblast-like synoviocytes (FLS) after exposure to pro-inflammatory cytokines, including TNF-α and IL-1β." (PMID 33114289, 2020). "For example, in rheumatoid arthritis (RA) animal models, NFAT5 has been shown to regulate macrophage function and participate in the disease’s pathogenesis." (PMID 40076009, 2025). "The role of NFAT5 as promoter of proinflammatory macrophage function has been further documented in mouse models as well as in studies in human rheumatoid arthritis (RA) patients." (PMID 30949179, 2019). "In rheumatoid arthritis NFAT5 expression was shown to be increased in the synovium and in synovial fibroblast-like cells the cytokines Il-1β and TNF-α strongly induced NFAT5 expression." (PMID 26495302, 2015).
diabetic nephropathy (11 papers, 2015 to 2024). "NFAT5 haploinsufficiency also alleviated renal macrophage infiltration in a mouse model of diabetic nephropathy." (PMID 33015193, 2020). "NFAT5 may also be a factor promoting fibrosis and tubular cell injury in non-diabetic kidney disease." (PMID 39595620, 2024). "Lnc‐ISG20 controlled NFAT5 expression by sponging miR‐486‐5p in diabetic nephropathy." (PMID 36852438, 2023). "In addition, Duan YR and colleagues highlighted that lnc-ISG20 facilitated NFAT5 through inhibiting miR-486-5p and induced renal fibrosis in diabetic nephropathy." (PMID 35012431, 2022). "The transcriptional activity of NFAT5 enhances AR expression under conditions of hyperglycemia in cultured peripheral blood mononuclear cells and human mesangial cells, which were isolated from patients with diabetic nephropathy." (PMID 33015193, 2020). "miR-486-5p also protects against ischemic kidney injury and targets PTEN, associated with decreased expression of select genes involved in apoptosis and the TNF inflammatory pathway, and may confer a protective anti-fibrotic role in diabetic kidney disease by targeting NFAT5." (PMID 35731367, 2022). "On the other hand, Nuclear Factor of Activated T-cells 5 (NFAT5), a transcriptional factor, is involved in the hypertonicity cellular response, renal ischemia, and reperfusion, hypoxia, and diabetic nephropathy." (PMID 35046888, 2021).
Insulin resistance (11 papers, 2015 to 2025). Increased resistance towards insulin, that is, diminished effectiveness of insulin in reducing blood glucose levels. "We summarize the pathogenic role of NFAT5 from four perspectives: AR, vascular complications, inflammation, and insulin resistance." (PMID 33015193, 2020). "High levels of NFAT5 are associated with the development of obesity and insulin resistance." (PMID 38612478, 2024). "It was found that elevated expression of NFAT5 due to the downregulation of miR-30b in adipocytes leads to the development of obesity and insulin resistance, whereas its ablation enhances adipocyte beiging and prevents ectopic deposition of triglycerides." (PMID 34064510, 2021). "NFAT5 suppresses the process of white adipocyte turning to beige adipocyte, which results in insulin resistance." (PMID 33015193, 2020). "NFAT5 promotes the formation of aldose reductase, pathogenesis of diabetic vascular complications, and insulin resistance." (PMID 33015193, 2020). "miRNA181a increases the expression of NFAT5 in a tonicity-independent manner, which substantially inhibits Treg cell induction and thereby contributes to the development of insulin resistance." (PMID 33015193, 2020). "Finally, NFAT5 depletion in myeloid cells significantly reduces inflammation and insulin resistance in mice with high-fat diet-induced obesity 170, underscoring its potential as a target for improving metabolic outcomes in obesity and T2DM." (PMID 40421201, 2025). "Through DNA methylation, NFAT5 suppresses the expression of the β3-adrenoreceptor gene (ADRB3), which is a critical regulator of lipolysis and thermogenesis, thus increasing the risk of insulin resistance." (PMID 33015193, 2020). "For example, NFAT5 can regulate thermogenesis and obesity by recruiting DNMT1 to the promoter of b3-adrenoceptor, a key regulator in thermogenesis and obesity, resulting in the suppression of thermogenesis and the beiging of white adipose tissue, leading to obesity and insulin resistance." (PMID 34064510, 2021).
colon carcinoma (10 papers, 2013 to 2025). "Some studies on breast and colon cancer have confirmed that the α6β4 integrin cluster promotes the expression of NFAT5 and the invasiveness and migratory capabilities of tumor cells." (PMID 29052520, 2017). "In colon cancer cells NFAT5-mediated upregulation of S100A4 has been shown to be stimulated by Integrins and Src kinase." (PMID 25152734, 2014). "Both NFATc2 and NFAT5 promote the migration and invasion of breast and colon cancer cells." (PMID 28235034, 2017). "Moreover, the metastasis-associated protein S100A4, which has been previously identified in colon cancer cells as an NFAT5 target gene, is very strongly upregulated in CaKi-1 cells." (PMID 25152734, 2014). "Similarly, TonEBP/NFAT5 induces metastasis in renal carcinoma and colon cancer cells." (PMID 38438872, 2024).
glioblastoma (10 papers, 2017 to 2025). The most malignant astrocytic tumor (WHO grade IV). "Increased NFAT5 activity enhanced glioblastoma cell-driven angiogenesis by mediating secretion of EGF like domain multiple 7 (EGFL7) via the miR-S38-3p axis." (PMID 39152497, 2024). "Moreover, miR‐138‐5p plays a tumor‐suppressing function in glioblastoma multiforme and colorectal cancer by inhibiting the expression of NFAT5 and ZEB2, respectively." (PMID 35441482, 2022). "Moreover, NFAT5 cpuld also promote glioblastoma cell-driven angiogenesis through EGFL7 which was mediated via SBF2-AS1 and miR-338-3p." (PMID 32863773, 2020). "In addition, compared with NHA, significant upregulation of NFAT5 was observed in U87 and U118 glioblastoma (GBM) cell lines." (PMID 28983240, 2017). "In glioblastoma multiforme (GBM), NFAT5 expression is markedly increased in both tumor samples and GBM cell lines, positively correlating with the WHO-GBM classification." (PMID 40421201, 2025).
Hyperglycemia (10 papers, 2013 to 2025). An increased concentration of glucose in the blood. "The hyperglycemia-induced miR-486 repression was reported to overexpress its target NFAT5, a transcription factor promoting renal fibrosis through AKT phosphorylation." (PMID 38804362, 2024). "Our data additionally revealed Nox4-induced ROS generation, hyperglycemia-induced mitochondrial dysfunction leading to reduced antioxidant capacity, NFAT5 overexpression, and glucose-induced upregulation of EGR1." (PMID 23149823, 2013).
Hypertension (10 papers, 2010 to 2025). The presence of chronic increased pressure in the systemic arterial system. "In arterial hypertension, chronic mechanical stress on blood vessels activates NFAT5, which promotes the expression of genes associated with vascular remodelling, inflammation, and fibrosis." (PMID 40421201, 2025). "In this section, we will explore the emerging role of NFAT5 in the extrarenal regulation of blood pressure and its implications for arterial hypertension and cardiovascular disease." (PMID 40421201, 2025). "These cells are essential in maintaining vascular tone, and NFAT5 supports their adaptive responses under osmotic and mechanical stress, conditions frequently encountered in the vasculature, particularly in hypertension." (PMID 40421201, 2025). "In conclusion, our findings suggested that hypertonic stress, similar to other atherogenic risk factors, such as hypertension, hyperlipidemia, and disturbed flow, promotes PAI-1 expression via NFAT5 in ECs, thus initiating endothelial dysfunction." (PMID 33410782, 2020). "The NFAT5-VEGFC-lymphangiogenesis axis also plays a crucial role in human arterial hypertension." (PMID 40421201, 2025). "Conversely, blocking NFAT5 or VEGF-C signalling aggravates hypertension." (PMID 21629436, 2010).
Obesity (10 papers, 2015 to 2026). Accumulation of substantial excess body fat. "Using a high-fat-diet (HFD) murine model, we investigated the regulatory role of the nuclear factor of activated T cells 5 (NFAT5s) in the obesity-induced LC damage and the resulting alterations in intergenerationally inherited sperm circRNA cargo." (PMID 42193266, 2026). "This suggests a negative regulatory role of NFAT5 in adipose metabolism and obesity, indicating its involvement in metabolic processes beyond its traditional role in osmotic stress response." (PMID 40421201, 2025). "NFAT5 could be an epigenetic regulator of thermogenesis and obesity." (PMID 40565529, 2025).
Arthritis (9 papers, 2019 to 2025). Inflammation of a joint. "Upregulated expression of NFAT5 was found in the synovia of patients with RA, and NFAT5 deficiency markedly inhibited the progression of an arthritis model." (PMID 32265505, 2020). "The decrease in arthritis severity in addition to macrophage infiltration was similarly reproduced in myeloid-specific Nfat5-deficient mice (LysM-Cre;Nfat5fl/fl mice), demonstrating a specific proarthritic effect of myeloid NFAT5 under high SAA concentrations." (PMID 38426494, 2024). "In murine models of arthritis, myeloid-specific NFAT5 deletion reduces disease severity, dendritic cell maturation, and the differentiation of pathogenic Th1/Th17 cells, further highlighting its role in pro-inflammatory immune responses." (PMID 40421201, 2025). "Injection of IL-6 into the affected joints also almost completely reversed arthritis reduction by NFAT5 deficiency, suggesting that IL-6, in addition to CCL2, mediates the progression of SAA/NFAT5 axis–dependent arthritis." (PMID 38426494, 2024). "Taken together, our data imply that LS diet modulates the p38 MAPK/NFAT5 signaling axis in the effector phase of arthritis, which is accompanied by a reduction of IL-1 beta expression resulting in decreased inflammation." (PMID 34925335, 2021). "For example, several researchers have confirmed that NFAT5 plays a pivotal role in the pathogenesis of RA, a tonicity-independent disorder, using various experimental arthritis models." (PMID 30873159, 2019). "Another work using the same NFAT5-haploinsufficient mouse model showed that these animals developed less severe arthritis than wild-type ones in an experimental model of collagen-induced arthritis." (PMID 30949179, 2019). "Interestingly, in collagen-induced arthritis models, NFAT5 expression is significantly reduced in mice on a low-salt diet, correlating with decreased arthritis severity compared to those on normal or high-salt diets." (PMID 40421201, 2025). "Moreover, in mice with SAA-accelerated arthritis, myeloid-specific depletion of Nfat5 mitigated infiltration of CCL2-expressing cells in the affected joints, particularly in infiltrating macrophages." (PMID 38426494, 2024). "Moreover, rescue experiments using recombinant IL-6 indicated that the SAA/NFAT5–induced increase in macrophage migration and arthritis progression also is dependent on IL-6." (PMID 38426494, 2024). "Rather, the SAA/NFAT5 axis may require an initial priming of synovitis repeatedly secreting a high amount of IL-1β and/or IL-6 so as to establish a chronic form of arthritis." (PMID 38426494, 2024). "Myeloid-specific depletion of NFAT5 also attenuated SAA-accelerated arthritis." (PMID 38426494, 2024). "Conversely, myeloid-specific depletion of NFAT5 attenuated SAA-accelerated arthritis." (PMID 38426494, 2024). "TLR-stimulated NFAT5 activates a sets of downstream target genes including Nos2, Il6, and Tnf that differ from osmolarity-associated target molecules, leading to macrophage activation and TLR-induced arthritis." (PMID 30873159, 2019). "Serum amyloid A (SAA) induces NFAT5 expression through TLR2/4-dependent pathways, promoting macrophage infiltration and arthritis progression in mice." (PMID 40421201, 2025). "However, the severity of SAA-accelerated arthritis was substantially diminished in Nfat5+/– mice compared with their WT littermates (Nfat5+/+), suggesting that the SAA/NFAT5 axis contributes to inflammatory arthritis in vivo." (PMID 38426494, 2024).